ENSG00000276965
Gene: Miscellaneous RNA gene on chromosome 22 (30,972,857 to 30,973,093, forward strand). Ensembl gene ENSG00000276965.
Gene Ontology:
Biological process: regulation of eye photoreceptor cell development